NGF (nerve growth factor)
Diseases named in the same sentence as NGF in open-access papers (continued):
Sharing a sentence is not in itself a finding about the gene and the disease.
osteoarthritis (continued). "Conventional management of canine osteoarthritis remains centred on long-term NSAIDs and, more recently, monoclonal blockade of nerve growth factor (bedinvetmab)." (PMID 41012844, 2025). "Numerous preclinical and clinical studies have shown local and systemic upregulation of NGF in chronic pain conditions such as rheumatoid arthritis, osteoarthritis, cancer, and degenerative intervertebral disc disease, suggesting an active role of NGF in pain." (PMID 39324959, 2024). "Anti-nerve growth factor antibodies bedinvetmab for dogs and frunevetmab for cats are licensed for the alleviation of osteoarthritis pain but their QOL impact is unreported." (PMID 39205806, 2024). "Chondrocytes in human osteoarthritis express NGF, and its level positively correlates with the degree of cartilage damage." (PMID 39553645, 2024). "While NGF mAbs provided beneficial pain relief to patients with arthritis, rapidly progressing osteoarthritis in some patients precluded FDA approval." (PMID 39589827, 2024). "A significant difference was found in the serum NGF concentration between the advanced osteoarthritis group (median, 238 pg/mL; IQR, 63‐945 pg/mL) and the lame group without radiographic changes in the affected joint (median, 31 pg/mL; IQR, 31‐95 pg/mL)." (PMID 37083137, 2023). "Nerve growth factor (NGF) has been suggested as a therapeutic target for osteoarthritis pain, and clinical trials with antibodies that neutralize NGF reported positive results in terms of pain relief." (PMID 37120427, 2023). "Current attempts to use anti-NGF antibodies and inhibitors have been successful in clinical trials of osteoarthritis, low back pain, and cancer-related pain." (PMID 37456526, 2023). "In a rat model of osteoarthritis, NGF increased in synovial membranes, chondrocytes, and subchondral bone after medial meniscectomy." (PMID 37083137, 2023). "Nerve growth factor concentration has been shown to be increased in synovial fluid and chondrocytes from joints of horses with naturally‐occurring osteoarthritis." (PMID 37083137, 2023). "The Nav1.8 is exclusively expressed on peripheral nociceptive neurons and has been shown to be relevant for NGF-induced thermal hyperalgesia, rodent models of osteoarthritis, nerve injury and inflammatory pain, and especially small-fiber neuropathy." (PMID 37443819, 2023). "Nerve growth factor (a-NGF) inhibitors have been developed for pain treatment including symptomatic osteoarthritis (OA) and have proven analgesic efficacy and improvement in functional outcomes in patients with OA." (PMID 37284331, 2023). "It remains to be determined if serum NGF concentration is increased in certain osteoarthritis disease stages or pain states." (PMID 37083137, 2023). "In humans, NGF is increased in serum of patients with osteoarthritis compared with healthy controls." (PMID 37083137, 2023). "Based on our study, on a group level, horses with advanced osteoarthritis have increased serum NGF concentrations." (PMID 37083137, 2023). "Few therapeutic feline chimeric or felinized antibodies have been reported to date, and the only commercially available one, called Frunevetmab, is a felinized anti-nerve growth factor (NGF) mAb, for alleviation of osteoarthritis pain in cats." (PMID 37095139, 2023). "CS in osteoarthritis is triggered by an increased expression of various cytokines, including nerve growth factor (NGF), in synovial inflammation." (PMID 36096936, 2022). "Novel developments include Fasinumab, a recombinant fully human IgG4, targeting the nerve growth factor (NGF) and evaluated for pain relief in patients suffering from osteoarthritis (OA)." (PMID 36134952, 2022). "Nerve growth factor (NGF) is an important mediator in chronic pain conditions and is upregulated in osteoarthritis (OA) and other rheumatic disorders." (PMID 35300334, 2022). "For instance, anti–nerve growth factor (anti-NGF) therapy has proven to be effective in reducing pain in osteoarthritis patients." (PMID 35608912, 2022).
osteoarthritis (continued). "Ligand binding of NGF to TrkA activates transcriptional and posttranscriptional pathways that mediate IL-1β release, while IL-1β induces chondrocyte inflammation and osteoarthritis via the NF-κB signaling pathway." (PMID 36292950, 2022). "Recently, the blocking of NGF was demonstrated to be an effective therapy for treating osteoarthritis." (PMID 35009001, 2022). "The cBPI was ultimately used as the primary outcome for the pivotal studies that lead to the approval of Galliprant® (a small molecule EP4 antagonist) and Librela ® (an anti-NGF monoclonal antibody) for the treatment of pain in dogs with osteoarthritis." (PMID 34421597, 2021). "The review misses several important trials and contains extraction/synthesis errors in the meta-analysis which resulted in authors overstating the efficacy of anti-NGF for patients with osteoarthritis and chronic low back pain." (PMID 33981217, 2021). "There has been a growing number of RCTs investigating the effect of medicines designed to inhibit the nociceptive effect of NGF for osteoarthritis and LBP." (PMID 33480861, 2021). "Systemic injection of a nerve growth factor (NGF) antibody has been proven to have a significant relevance in relieving osteoarthritis (OA) pain, while its adverse effects remain a safety concern for patients." (PMID 33806315, 2021). "Tanezumab, a human immunoglobulin-2 NGF antibody, is being studied for osteoarthritis (OA), chronic low back pain, and metastatic bone lesions, among others." (PMID 33987515, 2020). "Eligible studies should include randomized clinical trial-based investigations of anti-NGF antibody treatment for osteoarthritis pain and chronic low-back pain." (PMID 32694993, 2020). "Our observation is partially supported by a study where it has been shown that both the NGF-mRNA and the NGF protein were detected in macrophages isolated from patient with osteoarthritis, whereas the NGF-mRNA was also found in cultured mouse macrophages." (PMID 31996225, 2020). "NGF, detected in osteoarthritis synovial fluid, is an important mediator in hyperalgesia associated with inflammation." (PMID 32532064, 2020). "Recently, two classifications for rapidly progressive osteoarthritis have been adopted to characterize the rapid joint destruction observed in clinical trials for anti-nerve growth factor (NGF) agents." (PMID 32471412, 2020). "Increased NGF levels have been reported in rheumatoid arthritis, spondyloarthritis, and osteoarthritis patients." (PMID 31077183, 2019). "NGF has previously been implicated as a major mediator of bone pain in a number of diseases, including osteoarthritis, osteosarcoma and prostate cancer, and therapeutics which directly block NGF are undergoing trials for these diseases." (PMID 31578352, 2019). "Nerve growth factor (NGF) has emerged as a key driver of pain in osteoarthritis (OA) and antibodies to NGF are potent analgesics in human disease." (PMID 30862648, 2019). "More recent trials have not suggested a high frequency of these adverse events so it remains hopeful that anti-NGF therapies will become effective clinical tools for osteoarthritis." (PMID 31920521, 2019). "Studies of systemic diseases (i.e., diabetes mellitus and osteoarthritis) have revealed an interaction between NGF and TGF-β." (PMID 29867937, 2018). "Some studies suggest that TNF-α and IL-1β control the activity of NGF in human synovial fibroblasts modulating the physiopathology of osteoarthritis." (PMID 29867937, 2018). "The development of anti-NGF antibodies was re-initiated in 2015 in patients with osteoarthritis and low back pain (NCT02301234, NCT0252818, NCT02528253, and NCT02683239; at clinical trials.gov)." (PMID 28056917, 2017). "Nerve growth factor (NGF) sequestration has been trialed for the management of inflammatory bone pain (osteoarthritis), and there is significant evidence for interaction of NGF with bone marrow nociceptors." (PMID 28955292, 2017).
osteoarthritis (continued). "Further development of anti-NGF agents in patients with IC/BPS will be dependent on the safety profile observed in the osteoarthritis and low back pain studies." (PMID 28056917, 2017). "In humans, there were elevated NGF levels found in the synovial fluid of patients with inflammatory, rheumatoid arthritis or osteoarthritis." (PMID 27294371, 2016). "Human clinical studies of anti-NGF mAbs were halted by the FDA due to a signal of adverse events related to rapidly progressing osteoarthritis (RPOA) in approximately 1% of treated patients." (PMID 25926287, 2015). "A small number (16 of 6,800) of patients with OA that were treated with anti-NGF mAbs required joint replacement earlier than would be normally expected and this was attributed to “rapidly progressing osteoarthritis”." (PMID 24206926, 2013). "Anti-NGF mAb therapies are particularly attractive because of their potential to provide long-lasting analgesia in chronic disease settings, such as osteoarthritis and cancer pain." (PMID 24206926, 2013). "For all these reasons, there has been a great interest in the development of antagonists of NGF as analgesic drugs for chronic and inflammatory pain conditions such as osteoarthritis." (PMID 22403636, 2012). "Studies investigating a role for neurotrophins in the pathogenesis of osteoarthritis have shown upregulation of both NGF and Trk-A in osteoarthritic chondrocytes." (PMID 18727839, 2008). "This review aims to provide an updated overview of the potential clinical applications of anti-NGF monoclonal antibodies beyond osteoarthritis, analyzing their pathophysiological rationale, available scientific evidence, possible therapeutic advantages, and limitations that remain to be addressed." (PMID 41301953, 2025). "Further studies are needed to verify whether anti-NGF mAbs could be configured not only as analgesic drugs but also as Disease Modifying Osteoarthritis Drugs (DMOADs)." (PMID 41301953, 2025). "Therapies targeting NGF (e.g., anti-NGF monoclonal antibodies) have shown promise in osteoarthritis and may have applications in SARDs with prominent pain syndromes." (PMID 40649815, 2025). "For example, an NGF antibody tanezumab was applied to treat painful osteoarthritis, and administration of tanezumab could improve the pain symptoms of patients." (PMID 39718951, 2025). "They then applied this vaccination in a murine model of osteoarthritis, resulting in high anti-NGF antibody titers and reversibly alleviated pain behaviors (improved weight-bearing on the affected limb), both in prophylactic and therapeutic vaccination regimens." (PMID 41012116, 2025). "This temporal change in NGF expression during peripheral inflammation may help determine the timing of therapeutic interventions like anti-NGF antibodies for treating diseases like osteoarthritis and rheumatoid arthritis." (PMID 38612839, 2024). "Adverse effects, such as rapidly progressive osteoarthritis, may occur in some patients treated with anti-NGF antibodies, indicating that the presence of NGF plays an important role in maintaining the process of repairing damaged bone and cartilage." (PMID 39075502, 2024). "Antibodies targeting NGF (NGF-Abs) have been developed for treating chronic pain conditions such as osteoarthritis and chronic low-back pain, as NGF contributes to peripheral and central sensitization through the activation of TrkA and stimulation of local neuronal sprouting." (PMID 37998739, 2023). "Previously, the reduction of pain markers with a combination of senolytic drugs has been observed in an in vivo osteoarthritis model, where they observed a decrease in NGF, calcitonin gene-related peptide (CGRP) and selectively removed senescent cells, further supporting our findings." (PMID 37627322, 2023). "In addition to our therapeutic antibody, a caninized anti‐NGF monoclonal antibodies (ranevetmab) have been developed and shown to alleviates pain in dogs with degenerative joint disease." (PMID 36701408, 2023).
osteoarthritis (continued). "As NGF also plays an important role in the development and maintenance of pain in chronic inflammation, NGF antibodies have so far been used mainly in clinical trials on painful osteoarthritis." (PMID 37834436, 2023). "Whatever the reason, these adverse events indicate that serum NGF concentration increases as a result of osteoarthritis and is not a causative factor." (PMID 37083137, 2023). "Our observations support a key role for Piezo2 expressed by nociceptors in mediating mechanical sensitization associated with a mouse model of acute inflammatory knee pain, two mouse models of osteoarthritis, as well as with a model induced by local injection of NGF into the knee over 8 weeks." (PMID 37120427, 2023). "Anti-NGF antibody drugs include Pfizer/Lilly’s Tanezumab and Regeneron/Tiva’s Fasinumab, both of which have achieved significant efficacy in the treatment of moderate to severe osteoarthritis and chronic lower back pain." (PMID 36578547, 2022). "Therefore, NGF-targeted molecular imaging will assist to accurately visualize the source of osteoarthritis pain." (PMID 35717383, 2022). "Additionally, elevation of NGF expression levels has been identified in many clinical disorders, including rheumatoid arthritis, osteoarthritis, spondyloarthropathies, and lumbar degenerative disk disease." (PMID 35417079, 2022). "In addition to promoting ectopic nerve fiber sprouting, NGF promotes bone pain through sensitization of sensory nerve fibers, and anti-NGF treatments have shown efficacy in reducing pain from osteoarthritis and low back pain." (PMID 35262711, 2022). "Conjugation of NGF antibody with molybdenum disulfide nanosheet-coated gold nanorods (MoS2-AuNR) nanoprobes has been shown to active targeting of NGF on painful knees in an osteoarthritis surgical murine model." (PMID 35717383, 2022). "However, with tanezumab, an anti-NGF antibody, patients with osteoarthritis pain experience an analgesic response that differentiates from placebo as soon as 1 week after treatment." (PMID 34421597, 2021). "Moreover, the analgesic effect of the anti-NGF antibody NV-01 has been described in dogs with degenerative joint disease, who gained mobility and had decreased pain after treatment." (PMID 34638667, 2021). "Abs that inhibit the function of NGF and small molecule inhibitors of NGF receptors have been developed and tested in clinical studies to evaluate the efficacy of NGF inhibition as a form of analgesia in chronic pain states including osteoarthritis and chronic low back pain." (PMID 34638667, 2021). "Serum NGF has been associated with bone pain arising from sarcoma, prostate cancer and osteoarthritis, but has not been assessed in MM." (PMID 31578352, 2019). "As detailed above, bone cancers, fractures, osteoarthritis, and osteomyelitis produce inflammation that can activate peripheral bone marrow nociceptors through the release of inflammatory mediators, and these include growth factors such as NGF." (PMID 28955292, 2017). "Furthermore, inhibition of NGF action remarkably reduced hyperalgesia and pain perception in animal models with acute local inflammation, chronic inflammatory arthritis or osteoarthritis." (PMID 27294371, 2016). "Anti-NGF agents have been proposed to cure osteoarthritis and CMs that inhibit NGF responses could be used to develop drugs for osteoarthritis." (PMID 27453720, 2016). "NGF overexpression was found in animal models of experimentally induced osteoarthritis." (PMID 27294371, 2016). "One recent report suggested that this caninised anti-NGF mAb may provide alleviation of the signs of pain in dogs with osteoarthritis." (PMID 25926287, 2015). "Similarly, in synovial fibroblasts isolated from patients with osteoarthritis, both IL-1β and TNFα were shown to increase NGF synthesis and release." (PMID 18727839, 2008).
osteoarthritis (continued). "Furthermore, owing to the diverse biological effects of NGF, systematic administration of anti-NGF monoclonal antibody in patients commonly faces various adverse events, such as abnormal peripheral sensation or the progression of osteoarthritis or osteonecrosis." (PMID 37275761, 2023). "In response to mechanical or inflammatory stimuli, the nerve growth factor (NGF), which plays a key role in activating and sensitizing peripheral nerves, is secreted by articular chondrocytes and synovial fibroblasts, triggering pain in an osteoarthritis joint." (PMID 35717383, 2022). "Importantly, neutralizing this developmental process in the adult is a successful method for attenuating inflammatory pain in rodents and humans and NGF antibodies represent an important new class of disease modifying drugs effective for the treatment of osteoarthritis." (PMID 31920521, 2019). "Bedinvetmab (LibrelaTM), a monoclonal antibody (mAb) targeting nerve growth factor (NGF), represents a significant advancement in canine osteoarthritis (OA) pain management." (PMID 40417367, 2025). "However, long-term effects may be challenging to assess because NGF-sequestering therapeutics do not appear to readily cause rapidly progressing osteoarthritis, at least in dogs where bedinvetmab has been in clinical use for some time." (PMID 39959966, 2025). "The advent of anti-nerve growth factor (NGF) monoclonal antibodies, such as bedinvetmab (LibrelaTM), has marked a significant advancement in the management of osteoarthritis (OA) pain in dogs." (PMID 40948630, 2025). "AAVs expressing CRISPR-Cas9 were used to target NGF, IL-1β, and MMP13, which are commonly upregulated in osteoarthritis." (PMID 39598601, 2024). "Tanezumab, a monoclonal antibody that blocks nerve growth factor (NGF) signaling, has been shown to be effective in relieving the clinical symptoms of osteoarthritis pain, chronic low back pain, cancer pain induced by bone metastasis, and diabetic neuralgia." (PMID 35417079, 2022). "In a mouse model of post-traumatic osteoarthritis induced by destabilization of medial meniscus (DMM), the level of synovial NGF protein exhibited a significant increase at 4 weeks after surgery." (PMID 35717383, 2022). "Anti-NGF medicines have been tested in some chronic pain conditions, particularly LBP and osteoarthritis." (PMID 33480861, 2021). "Nonetheless one proposed use is for analgesia in osteoarthritis for which treatment can be required for many years, potentially impacting ganglionic neurons, although the high levels of receptor may be able to scavenge trace amounts of NGF and maintain neuronal integrity." (PMID 33424545, 2020). "The parallel with adverse outcomes seen in human anti-NGF trials—particularly rapidly progressive osteoarthritis—should not be overlooked." (PMID 40740305, 2025). "Prior studies outside of the context of bone irradiation have validated that upregulated osteoclast activity from other pathologies such as osteoporosis, osteoarthritis, and lower back pain can modulate the expression of CGRP, SP, and/or NGF, contributing to pain sensitivity." (PMID 40940736, 2025). "Prior studies outside of the context of bone irradiation have validated that upregulated osteoclast activity from other pathologies such as osteoporosis and osteoarthritis can modulate the expression of CGRP, SP, and/or NGF, contributing to pain sensitivity 35–37." (PMID 39011106, 2024). "Serum NGF concentrations in horses with advanced osteoarthritis with reaction to flexion in 1 vs all 4 limbs were not statistically different between groups." (PMID 37083137, 2023). "Marked differences were found between the group of sound horses and the group of lame horses with advanced osteoarthritis, with almost no detectable serum NGF in any of the sound horses." (PMID 37083137, 2023).